IDO1 (indoleamine 2,3-dioxygenase 1)
Diseases named in the same sentence as IDO1 in open-access papers (continued):
Sharing a sentence is not in itself a finding about the gene and the disease.
melanoma (continued). "Unfortunately, the phase III trial in melanoma patients (ECHO- 301/KEYNOTE-252) failed in confirming efficacy of epacadostat and pembrolizumab combination, leaving open question on the clinical relevance of Ido-1 inhibition in cancer treatment." (PMID 36419183, 2022). "Next, we investigated IDO1 and CD83 co-expression in SLN LCs from patients with melanoma." (PMID 35408802, 2022). "Contrary to expectation, clinical trials showed that inhibitors of the ubiquitously expressed enzyme, indoleamine-2,3-dioxygenase-1 (IDO1), do not provide benefits in melanoma patients." (PMID 33806305, 2021). "Interestingly, in melanoma CD4+ T cells, exhaustion was found to be related to the kynurenine pathway and IDO1 overexpression." (PMID 34439305, 2021). "In particular, treatment of melanoma with the use of Epacadostat (a selective inhibitor of IDO1) combined with pembrolizumab (an inhibitor of PD-1) does not offer significant advantages over placebo plus pembrolizumab." (PMID 34539663, 2021). "This study investigated the clinical relevance of IDO1 expression by immune cells in the lymph nodes and blood and of the serum kynurenine/tryptophan (Kyn/Trp) ratio in 65 systemic treatment naïve stage I-III melanoma patients." (PMID 34557196, 2021). "This study focused on the clinical significance of immune cell IDO1 expression in the lymph node and peripheral blood compartment as well as the significance of Trp metabolites in serum of 65 drug-therapy naïve stage I-III melanoma patients." (PMID 34557196, 2021). "Although selective and potent IDO1 inhibitors have shown promising results in experimental models of cancer, their benefit in melanoma patients has not been completely elucidated." (PMID 33806305, 2021). "Regarding combinations with immune checkpoint inhibitors, an indoleamine 2, 3-dioxygenase 1 (IDO1)-targeted therapy was a promising candidate, but the negative results of the phase 3 trial in malignant melanoma lessened the motivation for testing this target." (PMID 35006440, 2021). "By linear regression analyses, increased number of mitoses measured per 1 mm2 was correlated with overexpression of PARP1 in nuclei of mucosal melanoma cells (p = 0.0052) but not to IDO1 or PD-L1 expression." (PMID 32380691, 2020). "The 2018 phase 3 clinical trial (NCT02752074) that examined the effectiveness of combining an IDO1 inhibitor, epacadostat, with the checkpoint inhibitor pembrolizumab found that melanoma patient progression-free survival was not improved." (PMID 33109232, 2020). "IDO1/TDO2 inhibitors suppress tumor formation in animal models and are currently being evaluated in clinical trials against a wide range of cancers, including melanoma, glioblastoma, non–small cell lung cancer, and pancreatic and breast cancers." (PMID 32325928, 2020). "The potential interaction between PARP1, IDO1, and PD-L1 has not been studied in a large cohort of mucosal melanomas." (PMID 32380691, 2020). "IDO1 is more expressed than TDO in many tumours including melanomas; however, IDO inhibitors did not give expected results in clinical trials, highlighting the need to consider TDO." (PMID 32776284, 2020). "Moreover, IFNγ signatures (CXCL10, CXCL9, IDO1, IFNG, and STAT1) and myeloid lineage phenotypic and functional markers (CD14, CD163, CD33, and CD68) were also significantly increased in melanoma patients with high ETV7." (PMID 33424867, 2020). "A predominant expression of IDO1 in the tumor endothelial cell fraction was also noted in HCmel12 melanomas, but the level of IDO1 and of intratumoral IFNγ were not significantly increased by anti-CD40 therapy in this model." (PMID 32231867, 2020). "Here, we found a correlation between Kyn/Trp and IDO1 but not TDO mRNA levels in melanoma samples 4 weeks after nivolumab treatment." (PMID 31554815, 2019).
melanoma (continued). "IDO1 has also been reported to participate in a resistance mechanism to checkpoint inhibitors, and the combination of CTLA-4 blockade and an IDO1 inhibitor resulted in more effective antitumor immunity in a melanoma mouse model." (PMID 30068361, 2018). "Nevertheless, the LRP analyses detected IDO1, LAG3, TIM-3, VISTA, and CD40 in the 22 melanomas." (PMID 28546465, 2017). "Many murine tumors (with the notable exception of B16 melanoma) express IDO1 upon exposure to IFNγ, but none of them expresses IDO1 in the absence of IFNγ." (PMID 25691885, 2015). "With our analysis, based on IDO-1 expression, we strongly encourage to consider a possible IDO-1 inhibition therapy IDO-1 expression-driven and this could be the way to overcome the resistance observed in melanoma patients treated with IDO-1 inhibitors." (PMID 40475772, 2025). "Epacadostat, an IDO1 selective inhibitor, was evaluated in a randomized, placebo-controlled, double-blind, phase 3 trial (ClinicalTrials.gov Identifier: NCT02752074) in patients with unresectable stage III or IV melanoma previously untreated with PD-1 or PD-L1 inhibitors." (PMID 40092297, 2025). "Finally, we analyzed scRNA-seq data from two melanoma patients and specifically investigated whether combined HH/GLI and IFNγ/STAT1 signaling would affect the relative amount of IDO1 positive tumor cells." (PMID 39962447, 2025). "The analysis of a bulk RNA-seq data set with a mixed cohort of melanoma and non-melanoma skin cancer patients revealed a significant positive correlation of IDO1 with GLI2 (R = 0.39, p < 0.01), supporting an in vivo involvement of the HH/GLI pathway in the induction of IDO1." (PMID 39962447, 2025). "In vivo studies revealed that ART directly targeted Ido1 in B16F10 cells, decreased Hic1 levels, promoted Hmox1 transcription, facilitated ROS production and lipid peroxidation, aa and induced ferroptosis in melanoma cells, leading to cell proliferation inhibition in melanoma." (PMID 41160271, 2025). "Several phase 3 studies with linrodostat (BMS-986205), a selective IDO-1 inhibitor, in combination with nivolumab for the treatment of muscle-invasive bladder cancer (NCT03661320) and previously untreated metastatic or unresectable melanoma (NCT03329846) are ongoing." (PMID 39054430, 2024). "We demonstrate that HUVECs’ proliferation in response to the conditioned media of melanoma cells depends in part on TDO function since it is inhibited by 680C91, while IDO1 inhibition with epacadostat did not modify the proliferative potential of the melanoma-conditioned medium." (PMID 38794128, 2024). "However, there are some ongoing phase 3 studies, such as nivolumab in combination with linrodostat (BMS-986205), a selective IDO-1 inhibitor, for the treatment of muscle-invasive bladder cancer (NCT03661320) and previously untreated metastatic/unresectable melanoma (NCT03329846)." (PMID 39054467, 2024). "Epacadostat (INCB024360) was the first IDO1 inhibitor to advance into a phase III clinical trial (ECHO-301/KEYNOTE-252) after showing promising efficacy in advanced melanoma patients when combined with α-PD-1 antibodies in two nonrandomized, uncontrolled phase II trials." (PMID 39211039, 2024). "Consequently, tolerogenic immature IDO1+CD83-LCs could be involved in LNs metastasis arrival/homing and melanoma proliferation." (PMID 38791968, 2024). "However, the phase III clinical study of epacadostat a selective IDO-1 inhibitor in combination with pembrolizumab in melanoma patients (ECHO-301/KN-252) provided negative results." (PMID 37180110, 2023). "Notably, IDO1 inhibitors have already entered clinical trials, combined first with chemotherapeutic drugs and then with immune check-point inhibitors, such as anti-CTLA-4 and/or PD-1, to turn melanoma tolerance into anti-melanoma immunity." (PMID 35408802, 2022).
melanoma (continued). "Additionally, the potential value of various new inhibitory immune checkpoints (BTLA, B7 family, IDO-1, LAG-3) and costimulatory molecules (GITR, ICOS, OX40, 4-1BB, CD40, CD27) has been confirmed for melanoma treatments." (PMID 36125617, 2022). "Epacodostat, a hydroxyamidine analogue developed by Incyte Inc, was the first IDO1-selective inhibitor to complete Phase III evaluation in combination with Pembrolizumab, an anti-PD1 immune checkpoint blocker from Merck for the treatment of advanced malignant melanoma (ECHO-301/KEYNOTE-252)." (PMID 36145311, 2022). "However, clinical trials using inhibition of IDO1 in combination with blockade of the PD1 pathway in patients with melanoma did not improve the efficacy of treatment compared to PD1 pathway blockade alone." (PMID 34911954, 2021). "Whilst IDO1 inhibitors can boost immunotherapy in mouse cancer models, the most advanced IDO1 inhibitor Epacadostat (INCB024360) could not potentiate anti-PD1 inhibitor pembrolizumab in a recent Phase III trial involving about 700 advanced melanoma patients." (PMID 33708223, 2021). "Furthermore, we recently demonstrated the intrapatient heterogeneity of IDO1 between primary melanomas, and their corresponding lymph node and distant metastases." (PMID 34202352, 2021). "Both melanoma and hepatocellular carcinoma cells are able to inhibit the expression of NK receptors that trigger their immune function, including NKp30, NKp44, and NKG2D, with the impairment of NK-cell-mediated cytolytic activity against melanoma cells, through IDO1 and PGE2 expression." (PMID 33271839, 2020). "The efficacy of TRP2 peptides in generating anti-melanoma immune responses was also tested using a novel microparticle composed of yeast-expressing TRP2 peptide-loaded with PEI/siRNA conjugates for the co-delivery of indoleamine 2,3-dioxygenase (IDO1)-targeting siRNAs." (PMID 32532030, 2020). "However, experimentally, no detectable IDO1 expression is observed in most human tumor cell lines oriented from pancreas, cervix, colon, melanoma, possibly due to the absence of a complete cancer microenvironment in vitro." (PMID 26895379, 2016). "Notably, TRP depletion and KYN production may be promoted by SLN IDO1+ DC subsets, including pDCs, dDCs and LCs, leading to effector T cells impairment, enhancing Tregs, sustaining a tolerogenic microenvironment, promoting SLN melanoma metastases." (PMID 38791968, 2024). "Interestingly, the non-enzymatic apo-form of IDO1 is still active as a transducing protein, capable of promoting an immunoregulatory phenotype in dendritic cells (DCs) as well as a pro-tumorigenic behavior in murine melanoma." (PMID 38333210, 2024). "Thus, despite various initial data on the efficacy of IDO1 inhibitors in cancer immunotherapy, during recent clinical trials, adding epacadostat (an IDO1 inhibitor) to pembrolizumab (an ICB) had not made significant contributions to controlling metastatic melanomas." (PMID 36338522, 2022). "Importantly, SLN IDO1+ DC subsets (LCs, pDCs and dDCs) might be responsible for TRP depletion and KYN production, blocking effector T cells and enhancing T regulatory cells, therefore maintaining a tolerance milieu favoring SLN melanoma metastases." (PMID 35408802, 2022). "Consequently, intracellular epacadostat concentrations in melanoma could have been low, thus possibly not sufficiently inhibiting IDO1-mediated Trp degradation." (PMID 31819194, 2020). "The melanomas with brain metastases (BM) showed higher expression of CTLA-4, and lower expression of 4-1BB, CD163, GITR, IDO1, PR, EPCAM and ER-alpha than the melanomas without metastases." (PMID 40621453, 2025). "In the areas with tumor fields infiltrated by immune cells (CD45+/S100+ ROIs) melanomas with brain metastases (BM) showed lower expression of VISTA and IDO1 and no overexpression of genes when compared to tumors without metastases (NM)." (PMID 40621453, 2025).
melanoma (continued). "Melanoma patients who do not respond to ICI monotherapy frequently express alternate immune checkpoints, including IDO1." (PMID 40108693, 2025). "New compounds targeting IDO-1 have been under investigation in NSCLC and also in other malignancies such as melanoma, with no encouraging results." (PMID 40475772, 2025). "In order to better understand SLN LCs functional properties, the Authors focused on LCs IDO1 and CD83 relative expression in both melanoma-positive and negative SLNs." (PMID 38791968, 2024). "As previously introduced, during melanoma development, IFN-γ and IL-6 drive IDO-1 overexpression through a negative and positive feedback mechanism, respectively." (PMID 39062529, 2024). "As a matter of fact, in the present paper, we demonstrate that TDO inhibition, but not IDO1 inhibition, significantly reduced MMP-9 activity of melanoma cells co-cultured with endothelial cells." (PMID 38794128, 2024). "IDO1, expressed by both LCs and melanoma cells, lead to the production of KYN, which directly stimulate LCs to express more IDO1 trough AhR without inducing CD83 expression." (PMID 35408802, 2022). "Although the combination of IDO1 inhibitor (INCB024360) and pembrolizumab had encouraging results in phase I/II clinical trials of melanoma patients, it unfortunately failed to meet the endpoints in phase III trials." (PMID 34858835, 2021). "Our results show that, in SK-Mel-28 melanoma cells, dex up-regulated TDO and its downstream effector aryl hydrocarbon receptor (AHR) but not IDO1." (PMID 33806305, 2021). "We detected ISG.RS mRNA level in negative control or SOX2 KD melanoma cell lines and observed that SOX2 KD decreased the ISG.RS expression (IDO1, PDL1, IFI27, and USP16)." (PMID 33158915, 2020). "As COX-2 and autocrine PGE2 induce IDO-1 expression, melanoma cells treated with celecoxib showed a reduction in IDO-1 transcripts levels by 3-fold and no detectable IDO-1 protein." (PMID 32296574, 2020). "In the colon carcinoma CT26 and melanoma B16F10 cell lines, the expression of IDO1 is low or not detectable in cell culture." (PMID 33584686, 2020). "Despite promising results of some IDO1 inhibitors alone or in combination with PD1 inhibitors, their benefits in melanoma patients have not been completely demonstrated." (PMID 32776284, 2020). "While monotherapy with IDO1 inhibition has not demonstrated robust clinical activity, promising results have been demonstrated with the combination of the IDO1 inhibitor epacadostat (INCB024360) and ipilimumab in patients with advanced melanoma." (PMID 26850630, 2016). "Consequently, increased IDO1 expression in both APCs and melanoma cells could promote KYN-AhR interactions, stimulating peripheral LC and leading to a vicious cycle with further LCs IDO1 expression, but without improving CD83 expression." (PMID 38791968, 2024).
breast carcinoma (161 papers, 2009 to 2026). "The expression of TDO2 and IDO1 is upregulated in breast cancer, with high levels of TDO2 closely linked to poor patient prognosis." (PMID 39973065, 2025). "Among women with HR + breast cancer (BC), high IDO1 expression was associated with poorer long-term survival." (PMID 38539263, 2024). "Unexpectedly, Fang reported that higher IDO1 expression in breast cancer is associated with better overall survival (OS)." (PMID 38780888, 2024). "In contrast to human breast cancer and canine mammary tumors, examined rabbit mammary carcinomas displayed IDO1 staining only in tumor cells, whereas other tumor-associated cell populations, e.g., mononuclear immune cells and endothelial cells, were negative." (PMID 39061522, 2024). "Increased IDO1 expression in rabbit mammary carcinomas was also significantly associated with a lower mitotic count." (PMID 39061522, 2024). "To assess the clinical significance of IDO1 in breast cancer, we investigated the associations between IDO1 expression, clinicopathological variables, and OS." (PMID 38780888, 2024). "This indicated that mutations in PRKDC, NOS2, ARG1, and IDO1 were correlated to lower overall survival in breast cancer patients." (PMID 36373232, 2023). "Consistent with this, the overexpression of COX-2 described in mammary tumor cells is associated with increased IDO1 and kynurenine levels in co-cultured fibroblasts." (PMID 37296860, 2023). "High IDO1 expression is associated with poor outcomes in patients with breast cancer, and IDO1 promotes angiogenesis in breast cancer." (PMID 35760783, 2022). "It has been demonstrated that IDO1 deficiency reduced the density of the underlying pulmonary blood vessels and improved survival in primary lung carcinoma and breast carcinoma-derived pulmonary metastasis models." (PMID 35760783, 2022). "In breast cancer patients with high expression of IDO1/TDO2, low expression of KYNU was associated with a higher degree of tumor infiltration and lymphatic infiltration, whereas high expression of KYNU was significantly associated with a better level of prognosis in the patients." (PMID 41282989, 2025). "IDO1 expression in tumors, including breast cancer, is often associated with a worse prognosis, since IDO1 and its metabolites inhibit anti-cancer immune defenses and facilitate the survival, motility, and chemoresistance of tumor cells, as well as neo-angiogenesis and metastasis." (PMID 39061522, 2024). "Moreover, increased numbers of IDO1+ TAMs in breast cancer patients upregulated pro-tumourigenic factors associated with resistance to immunosuppressive therapy after anti-PD-1 treatment." (PMID 39351094, 2024). "Using cBioPortal, it was found that PRKDC (DNA‐PK encoding gene) tended to coexist with the functional markers of MDSCs which include NOS2 (iNOS‐encoding gene), Arg1 (Arg1‐encoding gene), and IDO1 (IDO‐encoding gene) in 19 breast cancer studies involving 9134 patients/9555 samples." (PMID 36373232, 2023). "In addition, higher tumor IDO1 expression was also associated with more advanced clinical stage and increased lymph node and distant metastasis in breast cancer." (PMID 32733806, 2020). "Both SLC7A5 and IDO1 exhibited markedly elevated expression in breast cancer tissues, with the highest levels observed in triple-negative breast cancer subtypes." (PMID 41179282, 2025). "It is clear that compared to the normal mouse mammary epithelial cell line HC11, a significant upregulation of IDO1 expression in the breast cancer cell lines 4T1." (PMID 39661740, 2025). "Consistent with our results, the mRNA expression of IDO1 was highest in the invasive basal‐like subtype of breast cancer." (PMID 39585774, 2025). "However, in specific cancer types like breast cancer, cervical squamous cell carcinoma, head and neck squamous cell carcinoma, ovarian cancer, lung adenocarcinoma, rectal adenocarcinoma, and sarcoma, elevated IDO1 expression is intriguingly associated with a more favorable prognosis." (PMID 41332472, 2025).